BRCA1 (BRCA1 DNA repair associated)
Diseases named in the same sentence as BRCA1 in open-access papers (continued):
Sharing a sentence is not in itself a finding about the gene and the disease.
lung carcinoma (continued). "CDK1 and CDK12 inhibition led to HR deficiency by decreasing HR repair proteins RAD51, BRCA1, and BRCA2 in lung cancer." (PMID 37370140, 2023). "Hu et al11 demonstrated that there were 64 (1.03%) carriers of BRCA1 and BRCA2 pathogenic germline variants in 6220 Chinese non‐small cell lung cancer (NSCLC) patients, with BRCA2 variants being the most predominant." (PMID 37930190, 2023). "For BRCA1, there was also an increase of carriers with an additional melanoma (9.52%) or lung cancer (9.52%) diagnosis." (PMID 36199081, 2022). "RUNX2 is a coregulator of BRCA1, the TF that regulates the LC-PAH CCP, strengthening the evidence that RUNX2 is associated with pulmonary arterial hypertension and lung cancer." (PMID 36551878, 2022). "BRCA1 is a prognostic biomarker in lung cancer, patients with high expression of BRCA1 have a poor outcome." (PMID 33936178, 2021). "We identified several germline and somatic mutations (e.g., BRCA1/2, PALB2, ATM, and ATR mutations) associated with HRD phenotype in ovarian, breast, pancreatic, stomach, bladder, and lung cancer." (PMID 34572800, 2021). "Poly(ADP-ribose) polymerase-1 (PARP) inhibitors have been FDA-approved for the treatment of breast cancer type 1 susceptibility protein (BRCA1)-mutated metastatic breast cancer, as well as ovarian and lung cancer." (PMID 32373151, 2020). "To this end, we employed the established H1299 lung cancer model allowing for DOX-inducible shRNA-mediated depletion of BRCA1 or BRCA2." (PMID 32085572, 2020). "Leveraging the available large-scale sequence data from TCGA and GTEX, we demonstrate that XIST, TSIX, hnRNPu, Bcl-2, and BRCA1 are differentially expressed in two different types of lung cancer when compared to controls." (PMID 33255394, 2020). "Our experiment on the OncoArray-TRICL data identified many one-way and two-way models with a single-base deletion in the noncoding region of BRCA1 (HR 1.24, P = 3.15 × 10–15), as the top marker to predict age of lung cancer onset." (PMID 33126877, 2020). "The expression of XIST and co-regulated genes TSIX, hnRNPu, Bcl-2, and BRCA1 analyses in lung cancer (LC) and controls were performed in silico." (PMID 33255394, 2020). "HMMR forms a complex with BRCA1 or BRCA2 together with other proteins, and high expression of HMMR was associated with poor survival in liver, pancreatic and lung cancer." (PMID 30785874, 2019). "BRCA1 has been considered as a predictor of treatment response and prognosis in breast, ovarian, and lung cancers; however, its role in mCRC and bevacizumab resistance is yet to be explored." (PMID 29342159, 2018). "Several examples include the v600E BRAF mutation, which predicts response to specific BRAF inhibitors, as well as high BRCA1 expression predicting resistance to neoadjuvant gemcitabine/cisplatin chemotherapy in lung cancer." (PMID 30352973, 2018). "To prove the finding that the synthetic lethal interactions were also existed in lung cancer, we have tested the autoantibodies to PARP1and BRCA1/BRCA2 in sera from lung cancer patients." (PMID 25865228, 2015).
lung carcinoma (continued). "Breast and lung cancer have many common prognostic signatures, such as hypermethylation of BRCA1, SOX17, and TLX3." (PMID 24842468, 2014). "Over expression of BRCA1 has been demonstrated in lung cancer and sporadic ovarian cancer where it was reported to lead to chemoresistance." (PMID 24403257, 2013). "First, we compared the expression of six molecular biomarkers (MDR-1, LRP, RRM-1, EGFR, ERCC-1, and BRCA-1) in the primary lung carcinoma and the metastatic lymph nodes of patients with the two subtypes of NSCLC." (PMID 22890830, 2012). "There have also been reports on the better survival in patients with BRCA1-negative tumor compared with those with BRCA1-positive one, as exemplified in breast and lung carcinomas." (PMID 19690636, 2007). "Indeed, in BRCA1- or ATM-mutated breast, ovarian and lung cancer lines, low EME1 levels associated with decreased Olaparib sensitivity, which was not the case in BRCA2-mutated or unaltered cells." (PMID 39994444, 2025). "Furthermore, DDR mutations, such as ATM, PTEN, MRE11, and FANCA mutations, have been found in a large proportion of lung cancer patients, as well as BRCA1/2 mutations in 5% of patients, justifying the administration of PARP inhibitors to lung cancer patients." (PMID 37682974, 2023). "In fact, when their prevalence in the controls was taken into account, P/LP variants of BRCA1 but not BRCA2 were significantly related with an elevated risk of lung cancer, as demonstrated by our study." (PMID 37930190, 2023). "Similarly, pathogenic germline variants in BRCA1 and BRCA2 were detected in 6 (0.34%) and 16 (0.79%) participants, respectively, in another study which involved 1764 Chinese lung cancer patients." (PMID 37930190, 2023). "However, this did not imply that BRCA2 played a more important role in Chinese lung cancer patients than BRCA1." (PMID 37930190, 2023). "Our results support the notion that PARP inhibitors administered in combination with immunotherapy using EGFR/Notch bsAbs have broad potential for the treatment of various tumours beyond hereditary BRCA1-deficient and BRCA2-deficient tumours, including lung cancer." (PMID 37441599, 2023). "While lung cancer is not typically related to germline BRCA1/2 mutations, there have been a few instances: there are somatic in the BRCA1 or BRCA2 gene in approximately 5-10% of non-small cell lung cancer cases." (PMID 36249053, 2022). "Our meta-analysis showed that individuals who are BRCA1 or BRCA2 carriers do not have an increased risk of lung cancer." (PMID 32349445, 2020). "However, the low frequency of the genomic alterations in cell lines has also been observed in other vulnerabilities (e.g., MET mutations in lung cancer or BRCA1/2 in BC), and this fact has not impacted the clinical development of strategies against them." (PMID 33671201, 2021). "BRCA1, a tumor-suppressing protein, epigenetically represses miR-155 in lung cancer cell lines, and the inhibition of miR-155 may have anti-cancer potential in sensitizing hypoxic lung cancer." (PMID 32650508, 2020). "Overall, our findings indicated that ANRIL reduces Rad51 and BRCA1 expression by targeting miR-7-5p/PARP1, which ultimately leads to radiotherapy resistance in lung cancer cells." (PMID 36755223, 2023).
lung carcinoma (continued). "Variants in both BRCA1 and BRCA2 were present across all histologies of lung cancer and controls, with a prevalence of 20.0% (12/37) and 6.3% (1/16) for BRCA1, and 18.3% (11/37) and 18.8% (3/16) for BRCA2 in lung cancer patients and controls, respectively." (PMID 34217228, 2021). "It has been reported that hsa-miR-342-3p regulates BRCA1 expression and MYC transcriptional activity by directly repressing E2F1 in human lung cancers." (PMID 32182819, 2020). "In terms of lung cancer, it has been suggested that high levels of DNA repair inhibiting proteins, such as SLFN11, and low levels of DNA repair promoting proteins, including ATM, may be a superior predictive biomarkers to BRCA1/2 mutations in small cell lung cancer." (PMID 32850380, 2020). "Both BRCA1 and PCNA are critical regulators for DNA replication and repair, whose potential to act as prognostic indicators in lung cancers have been well-documented." (PMID 33097805, 2020). "The following literature review confirmed that six of the nine TFs, including E2F8, MEIS, E4F1, BRCA1, GATA6, and IRX2, play essential roles in lung cancer progression." (PMID 29303984, 2018). "The BRCA1 and BARD1 genes and proteins play crucial role in the development of various cancers other than lung cancer." (PMID 28786985, 2017). "This high prevalence of autoantibody to PARP1 (22.4%) was notable, and meanwhile there was very low frequency of autoantibodies to BRCA1 (4.3%) and to BRCA2 (1.1%) in lung cancer sera." (PMID 25865228, 2015). "We further analyzed representative HRR and NHEJ marker proteins, including the levels of BRCA1 and RAD51 (for HRR) and the level of phosphorylated DNA-PKcs at T2609 (for NHEJ), in four lung cancer cell panels with different FHIT statuses and two FHIT-isogenic cell pairs." (PMID 39762409, 2025). "The results revealed that both wild-type and hydrolase-dead mutant FHIT successfully reduced the BRCA1 and RAD51 protein levels in FHIT−/− lung cancer cells, suggesting that the Ap3A hydrolase activity of FHIT is not crucial for HRR protein stability or DNA damage repair signaling." (PMID 39762409, 2025). "The role of BRCA1/2 in NSCLC remains controversial, with some studies demonstrating that the variants are associated with an increased risk for lung cancer, while others do not." (PMID 38539485, 2024). "We demonstrated variable prevalence of these two methylation events across cancer types, ranging from rare (e.g. BRCA1 methylation in lung cancer) to highly prevalent (e.g. RAD51C methylation in STAD and BRCA1 methylation in individuals of African ancestry with BC)." (PMID 39055334, 2024). "Furthermore, previous studies have increasingly shown that the expression of BRCA1 and the relevant poly (ADP‐ribose) polymerase inhibitors is related to the prognosis and therapeutic response of other tumors, including lung cancer." (PMID 38090061, 2023). "The second suggests a cooperative function between RUNX2 and three transcription factors (BRCA1, FOXM1, and RUNX1) important for the specific regulation of lung cancer establishment and progression, along with three transcription factors (E2F3, FHL2, and TWIST1) of the NSCLC-GRN." (PMID 36551878, 2022). "This study showed that families with BRCA1 or BRCA2 have no increased risks for lung cancer on the basis of current available studies." (PMID 32349445, 2020). "For cancer types not included in our BRCA1/2-associated FCH criteria, the most common malignancies were gastric, colorectal, and lung cancers, observed in 49 (10.3%), 30 (6.3%), and 28 (5.9%) patients, respectively." (PMID 33351846, 2020). "Only works that included a direct gene test cohort study and were selected for our meta-analysis revealed that lung cancer incidence was not increased in BRCA1 or BRCA2 carriers." (PMID 32349445, 2020).
lung carcinoma (continued). "In lung cancer cells, there was no variation (A549) or a slight decrease (H1975, H1650, H1299) of BRCA1 mRNA upon chemotherapy doublet treatment, with no potentiation by the p38 inhibitor." (PMID 28008145, 2017). "In order to verify whether the new combi-molecule could target BRCA1/2 mutants, we analyzed the potency of EG22 against the pair of Chinese Hamster lung cancer cell line: with V79, a BRCA1/2-proficient and the other VC8 BRCA1/2-mutant." (PMID 28800752, 2017). "In lung cancer sera, 22.4% (21/94) was shown to have autoantibody to PARP1, 4.3% (4/94) was shown to BRCA1, 1.1% (1/94) was shown to BRCA2, 4.3% (4/94) was shown to PARP1 and BRCA1, and 0% (0/94) was shown to PARP1 and BRCA2." (PMID 25865228, 2015). "However, seven BRCA1 and six BRCA2 germline truncations (MAF≤0.05%) were detected in other cancer types (three each in endometrial, stomach and lung cancers, two in kidney cancer and one each in prostate and head and neck cancers)." (PMID 26689913, 2015). "The reason for this difference might be that there was no synthetic lethal interactions between PARP1 and BRCA1/BRCA2 in lung cancer or there might be existed other types of synthetic lethal interactions, which is supported by recent studies." (PMID 25865228, 2015). "Furthermore, CCNB1 and CCNA2 were vital in regulating cell cycle progression, while BRCA1 was involved in DNA repair, damage, and chromatin remodeling and DHX15 overexpression has been shown to promote proliferation and tumor metastasis, particularly in lung cancers." (PMID 38233752, 2024). "The protein expression of hMLH1, hMSH2, XRCC1, XRCC3, XRCC5, BRCA1, and BRCA2 repair genes in B[a]P-treated HPV-positive and -negative lung cancer cells was analyzed by western blotting." (PMID 26918347, 2016). "Companion diagnoses, such as MSI, ERBB2 staining, EGFR, BRAF, ALK fusion, and BRCA1/2, can be done before the standard treatment, which is another reason why the CGP test is not needed, as the drivers of lung cancer, colon cancer, and melanoma are already known to a certain extent." (PMID 36251535, 2023).
melanoma (130 papers, 2007 to 2026). A malignant, usually aggressive tumor composed of atypical, neoplastic melanocytes. "We estimated the cumulative risk of melanoma between age 20 and 80 years to be 2.5% for women who carry BRCA1 mutations and 2.3% for women who carry BRCA2 mutations." (PMID 38741145, 2024). "We found the risk for melanoma in BRCA1 and BRCA2 mutation carriers to be only slightly higher than expected, based on US population rates." (PMID 38741145, 2024). "Between age 40 and 79 the annual risk for melanoma was 0.09% for BRCA1 carriers (90/100,000 per year) and 0.12% for BRCA2 carriers (120 per 100,000 per year)." (PMID 38741145, 2024). "The cumulative risk of melanoma was 2.5% for BRCA1 carriers and 2.3% for BRCA2 carriers, compared to 1.5% for women in the general population in the United States." (PMID 38741145, 2024). "The lifetime risk of melanoma was approximately 2.5% for women who carried BRCA1 mutations and 2.1% for women who carried BRCA2 mutations, compared to 1.5% for white women in the general population in the United States." (PMID 38741145, 2024). "For instance, CX-5461 is utilized for the treatment of BRCA1/2 deficient tumors through topoisomerase II inhibition, and melanoma cell lines have been treated with G4 ligand RHPS4 that targets the MYC gene among others." (PMID 36980918, 2023). "An interesting study reported the effect of PARPi on PDX of melanoma cells with the following differential HR statuses: MM425X (BRCA1 and ARIDB1 mutated), MM390X (CHD2 mutated) and MM507X (wild type)." (PMID 35563772, 2022). "Recently, the anti-tumor activity of niraparib was demonstrated in melanoma cell lines with mutations in BRCA1, ARID1,B and CHD2." (PMID 34831002, 2021). "For example, the rate of BRCA1/2 mutations is lower in melanomas compared to breast, ovarian, and prostate cancers." (PMID 34831002, 2021). "Another recent analysis of human melanoma found that 21.4% of this tumor type has at least one HRD gene mutation including BRCA1, ARID1A, ATM, ATR and FANCA." (PMID 34885093, 2021). "That said, on balance, it seems unlikely that germline BRCA1 or BRCA2 variants profoundly contribute to any melanoma subtype." (PMID 31610093, 2020). "For several decades, the role of germline BRCA1/BRCA2 variants in predisposition to melanoma has been controversial." (PMID 31610093, 2020). "High TOMM40 levels are associated with a super-invasive subtype of melanoma, with BRCA1/2 expression and mutations and is a histological feature for the squamous subtype of non-small cell lung cancer." (PMID 32635403, 2020). "The sequence analysis performed on the proband paraffin-embedded melanoma samples revealed the presence of the two BRCA1 and BRCA2 variants and a novel BRCA2 c.4297G>A somatic variant (p.Gly1433Arg)." (PMID 29346284, 2018). "The association between melanoma and BRCA1/2 mutations remains an open question which needs clarifications." (PMID 27776349, 2017). "Many of these melanoma-subordinate syndromes are associated with well-established predisposition genes (e.g., BRCA1/2, PTEN)." (PMID 28283772, 2017). "Further support for the role of BRCA1 in DDR deficiency was the low BRCA1 expression in melanomas correlating with poor survival as shown by Kaplan-Meier analysis." (PMID 23940574, 2013). "Germline and somatic mutations in BRCA1 elevate melanoma risk and contribute to its progression." (PMID 39061157, 2024). "For BRCA1 patients, studies inconsistently report increased risk of colorectal, prostate, and pancreatic cancer, as well as cancer of the uterine body and cervix, stomach, fallopian tube, and melanoma." (PMID 38067403, 2023). "Research evaluating the association between BRCA1/2 mutations and skin cancers is limited; indeed, while no studies showed a statistically significant association between BRCA1 mutations and melanoma, the surveys investigating BRCA2 mutations and melanoma produced inconsistent conclusions." (PMID 35573021, 2022).